OGG1 (8-oxoguanine DNA glycosylase)
Diseases named in the same sentence as OGG1 in open-access papers (continued):
Sharing a sentence is not in itself a finding about the gene and the disease.
tumor (78 papers, 2002 to 2025). "Consistent with a tumor suppressor role by preventing mutagenesis, treatments with oxidant KBrO3 increase G to T mutations in both Mutyh KO and Ogg1 KO mice, but only the Mutyh KO mice show increased tumorigenesis." (PMID 39837827, 2025). "Taken together, more samples and further studies are needed to elucidate the relationship between OGG1 Ser326Cys polymorphism and tumor susceptibility." (PMID 36497058, 2022). "Due to the critical role of OGG1 in 8-oxoG repair, the impact of OGG1 gene mutations, such as polymorphisms, have also received special attention, especially in the context of tumor development." (PMID 36497058, 2022). "Another tumor (N701T) with a very high frequency (78%) of C > A substitutions carried a germline missense variant in OGG1 (NP_002533.1:p.Gly308Glu) and a CNL of the other OGG1 allele." (PMID 34479993, 2021). "We have applied MD to analyze the structures of somatic tumor variants of OGG1, an important DNA repair protein, and to predict their consequences." (PMID 33361155, 2021). "The authors of the genetic study anticipated that a decreased amount of OGG1 in the BRCA1-deficient tumour is likely to sensitize it to PARPi therapy." (PMID 31329989, 2019). "Association of decreased levels of OGG1 with tumor development and/or progression has been well established." (PMID 23697596, 2013). "OGG1 expression therefore preserves genomic integrity, and it has been shown that Ogg1-deficient mice experience enhanced incidences of mutations and tumor formation." (PMID 20718982, 2010). "The decrease OGG1 expression is also associated with significant decrease in the transcription factor, NF-YA, expression in tumor samples compared to normal tissues." (PMID 19265534, 2009). "Loss of tuberin was associated with loss of OGG1 and significant decrease in NF-YA in tumor kidney tissue of Eker rats." (PMID 20040097, 2009). "The increase in tuberin phosphorylation and the decrease tuberin expression are associated with decrease in OGG1 protein and mRNA levels in tumor samples compared to normal kidney samples." (PMID 19265534, 2009). "In summary, tuberin deficiency in tumor kidney tissue of Eker rat is associated with decreased in NF-YA and OGG1 expression." (PMID 20040097, 2009). "Notably, RNA-Seq analysis following OGG1 knockdown revealed a significant reduction in tumor cell adhesion-related pathways, which suggested that OGG1 is closely linked to tumor initiation and progression." (PMID 40227353, 2025). "Thus, neoplasms of low malignant potential were distinct from others with respect to genotype distribution of both the OGG1 Ser326Cys and the ERCC6 Met1097Val polymorphisms." (PMID 26649138, 2016). "Thus, somatic mutations in the OGG1 gene in tumor cells could affect their sensitivity to therapeutic interventions." (PMID 33361155, 2021). "OGG1 facilitates tumor metastasis by assisting the transcription factor NF-κB in regulating the expression of SYT7." (PMID 40227353, 2025). "This regulatory function enables OGG1 to contribute to the adaptation of tumor cells to oxidative stress, thereby influencing cell survival and proliferation." (PMID 40227353, 2025). "During this process, OGG1 plays a crucial role in maintaining genome stability and cell viability in tumor cells by efficiently repairing oxidative DNA damage." (PMID 40227353, 2025). "By unraveling this complex relationship, we can gain a deeper understanding of OGG1’s role in tumor development and potentially identify novel therapeutic targets." (PMID 40227353, 2025). "Cell adhesion molecules were significantly downregulated following OGG1 knockdown, which contributed to understanding OGG1’s role in tumor initiation and progression and offering a basis for potential OGG1-targeted therapies." (PMID 40227353, 2025). "It showed that OGG1 knockout significantly reduced tumour metastasis after 5 days postfertilisation (dpf)." (PMID 39235072, 2024).
tumor (continued). "Collectively, our study illuminates the significance of 8‐oxoG/OGG1/SYT7 axis‐driven EVs release in oxidative stress‐induced tumour metastasis." (PMID 39235072, 2024). "Altogether, these results suggested that OGG1 has important functions in EVs release and tumour metastasis when responding to oxidative stress." (PMID 39235072, 2024). "Together, our data reveal that SIRT2 acts as a tumor suppressor by promoting OGG1 transcription and increasing BER efficiency in an ATM/ATR-dependent manner." (PMID 38554113, 2024). "Based on these findings, we propose a novel pathway by which OGG1 reads oxidative DNA signals and promotes EVs secretion and subsequent tumour metastasis." (PMID 39235072, 2024). "The expression levels of mitochondria tumor-suppressor and DNA-repair proteins (PGC-1α, TFAM, OGG1, MTUS1, and SIRT3) were examined in tumor samples from patients with OSCC to determine the association of these proteins with patient outcomes." (PMID 37627097, 2023). "Here, we explore and discuss the intricate connections between redox imbalance, oxidative DNA base modifications, and the interactions of OGG1 with NFκB and Myc in the tumor microenvironment." (PMID 38201575, 2023). "This aspect is very dysregulated in the TPC-1 tumor cell which shows a strong expression of OGG1 despite the inhibition of AKT." (PMID 35269445, 2022). "OGG1 depletion, or OGG1 inhibition, can rescue cells from lethality resulting from ROS-inducing agents; therefore, the role of OGG1 inhibitors in tumor therapy still needs to be further elucidated." (PMID 36497058, 2022). "OGG1 is necessary to maintain the proliferation of tumor cells, tightly involving in the occurrence and development of multiple cancers." (PMID 36528059, 2022). "Accordingly, we decided to probe the function of a different DNA damage repair protein, Ogg1, a tumor suppressor and glycosylase involved in the repair of ROS-induced 8-oxoG base lesions." (PMID 34685753, 2021). "We first measured the protein expression in the PGC1β/OGG1 signaling pathway in tumor tissues and found that treatment with shHKDC1 (shHKDC1/EMP) significantly decreased the levels of the PGC1β, HDKC1, and OGG1 proteins." (PMID 33423158, 2021). "Suppression of the EBV genome inhibited the expression of the LMP1/PGC1β/HKDC1/OGG1 signaling pathway, forming a positive feed forward loop for the generation of ROS, hence inhibiting the EBV genome and subsequent EBV-associated tumor development." (PMID 33423158, 2021). "Tumor organoid models with CNL of OGG1 or MUTYH show increased 8-oxoG levels compared to wild-type cells." (PMID 34479993, 2021). "Increased tumor burden has also been demonstrated in Ogg1-/- mice that were exposed to conditions of chronic DSS treatment." (PMID 31935236, 2020). "A decreased expression of OGG1 is related to tumor growth and progression because DNA-repairing ability can very frequently contribute to genomic instability." (PMID 32455559, 2020). "The involvement of reactive oxygen free radical sensor genes, the oxidative DNA damage (OGG1) repair gene and induction of pro-apoptotic genes suggest that reactive free radical species play a role in topotecan-induced tumor cell death." (PMID 32765594, 2020). "In contrast, OGG1 activity was found significantly higher in leukocytes and tumor tissues of CRC patients." (PMID 33004944, 2020). "After adjusting for potentially prognostic factors, XRCC1 rs25489 and OGG1 rs1052133 had a significant impact on primary tumor efficacy at the end of radiotherapy." (PMID 29108254, 2017). "The human OGG1 gene (hOGG1) is found on chromosome 3p26.2, which is one of the most frequent regions of genomic deletion and contains potential tumor suppressor genes for various types of tumors (e.g., NSCLC)." (PMID 28039450, 2017). "In relation to OGG1, a significant downregulation was observed in the tumor samples compared to the normal samples, as well as all clinical, histopathological data." (PMID 25268610, 2014).
tumor (continued). "In patients with or without some degree of tumor invasion, a significant downregulation in OGG1 was observed in tumor tissue." (PMID 25268610, 2014). "Tumor homogenate from cortex kidney of Eker rat show null tuberin and OGG1 expression indicating that tuberin is an upstream regulator of OGG1 protein and gene expression." (PMID 18218111, 2008). "We investigated the distribution of protein expression and the activity of OGG1 and 8-oxo-dG and correlated it with the expression of tuberin in kidneys of wild type and Eker rats and tumor from Eker rat." (PMID 18218111, 2008). "This suggests that OGG1 may recognize the substrates on DNA, and through chromatin modification, inhibit tumor suppressor gene expression, thereby promoting tumor development." (PMID 39741341, 2025). "Could the pro-inflammatory effect of OGG1 be the etiological link connecting 8-oxoG with tumor development and progression?" (PMID 39741341, 2025). "Notably, OGG1 deletion led to reduced SP1 binding at this site, underscoring OGG1’s role as an upstream regulator of gene expression under oxidative stress and its significance in tumor development." (PMID 40227353, 2025). "Thus, to validate the function of OGG1/SYT7 axis in tumour metastasis, we first expressed SYT7 in OGG1‐knockdown or OGG1‐knockout cells." (PMID 39235072, 2024). "Furthermore, we knocked out OGG1 using CRISPR/Cas9 technology and the results were consistent with those obtained from OGG1‐knockdown cells, highlighting the criticality of OGG1 in mediating oxidative stress‐induced tumour migration and invasion." (PMID 39235072, 2024). "Collectively, these data suggested that OGG1/SYT7 axis played a crucial role in tumour metastasis, which could be effectively suppressed by OGG1 inhibitor." (PMID 39235072, 2024). "Our data reveal that OGG1/SYT7 axis is important for oxidative stress‐induced tumour metastasis, which could be effectively suppressed by OGG1's DNA binding inhibitor Th5487." (PMID 39235072, 2024). "Given our substantiated evidence regarding the pivotal role played by EVs release in oxidative stress‐induced cell migration and invasion, we next wondered whether OGG1, as the oxidative DNA sensor, could regulate EVs secretion to promote tumour metastasis." (PMID 39235072, 2024). "Consistent with previous study showing that timely orchestrated DNA oxidation associated with LSD1 is required for transcriptional initiation in tumor progression, we demonstrate that not only 8-oxoG and chromatin remodeler but also OGG1 are essential for EMT gene expression." (PMID 36651270, 2023). "This suggests that oxidative DNA damage is involved in the upregulation of PD-L1 in response to exogenous oxidative stress, and combination with an OGG1 inhibitor may improve tumor therapy strategies targeting PD-L1/PD-1." (PMID 36497058, 2022). "The increase in OGG1 was detected in several tumor cells treated to suppress mTOR activity." (PMID 35269445, 2022). "Moreover, the expressions of Nrf2 and OGG1 in tumor tissues were identified by immunohistochemistry (IHC) assay." (PMID 36528059, 2022). "OGG1 is expressed in normal tissues, and in most tumor tissues." (PMID 34227370, 2021). "This caused a regression in tumor size in xenografts harboring OGG1-targeting shRNA, whilst tumors with non-targeting shRNA were unaffected." (PMID 33211885, 2020). "The DNA repair activity of multiple lesion-specific DNA glycosylases, such as MPG, SMUG1, UNG, NTH1, NEIL1 and OGG1 could be readily detected in lysates from human tumor cells (LN428, U2OS and K562 cell lines) and normal cells (PBMCs)." (PMID 30167090, 2018). "Several key repair genes play important roles in BER pathway, such as the X-ray repair cross-complementing 1 (XRCC1), 8-oxoguanine DNA glycosylase (OGG1), and apurinic/apyrimidinic endonuclease 1 (APEX1) genes, which are associated with human tumor susceptibility and radiation toxicity." (PMID 29108254, 2017).
tumor (continued). "However, only PARP-1 mRNA in tumor significantly exceeded that in normal tissue (p = 0.00006), for OGG1 the differences were statistically insignificant (p = 0.24)." (PMID 25526641, 2014). "In addition decrease tuberin expression is associated with significant decrease in the mRNA and protein levels of OGG1 in tumor tissue compared to control tissue." (PMID 19265534, 2009). "Furthermore, Gene Ontology (GO) and KEGG enrichment analyses of the significantly downregulated genes also indicated that these genes are primarily involved in cell adhesion and migration, which is consistent with previous reports linking OGG1 to tumor cell migration." (PMID 40227353, 2025). "Notably, the effect of OGG1 knockout on tumour metastasis can be rescued by SYT7 overexpression." (PMID 39235072, 2024). "Downregulation of OGG1 might sensitize tumor cells to anticancer drugs by accumulating DNA damage." (PMID 33477262, 2021). "However, it has been subsequently shown that MTH1-null animals do not possess elevated levels of the hallmark G -> T tranversions expected due to increased genomic 8-oxoGua incorporation and, in fact, their tumor incidence is abolished in the OGG1-null background." (PMID 28481306, 2017). "Consequently, OGG1 could serve as a node linking oxidative DNA damage to tumor development." (PMID 39741341, 2025). "The pathophysiological implication of OGG1 in promoting NFκB, SP1, TFIID, SMADs, Myc, as well as p-RNA Pol-II and transcription, for immune responses and Myc-induced tumor progression, holds unforeseen significance." (PMID 38201575, 2023). "Our results suggested that Tf-D-HKC8 peptide-mediated interruption of HKDC1 suppressed tumor growth with overexpression of SOD2 and OGG1 completely and partly reversing this effect, respectively." (PMID 33423158, 2021). "Our results suggested that knocking-down HKDC1 suppressed the PGC1β/OGG1 signaling pathway in addition to the replication of EBV and tumor growth in a mouse model." (PMID 33423158, 2021). "In contrast, overexpression of either SOD2 or OGG1 suppresses oxidative stress-induced EBV DNA damage, thus preventing the HKDC1 interruption-induced suppression of EBV and tumor growth." (PMID 33423158, 2021). "In the present study, OGG1 was significantly decreased by TPT treatment, suggesting decreased repair of OH radical-mediated 8-oxoguanine and enhanced tumor cell killing." (PMID 32765594, 2020). "8‐oxo‐dG accumulation in the tumor is determined by multiple factors: 1 ROS‐induced production of 8‐oxo‐dG or 8‐oxo‐dGTP, 2 sanitization of 8‐oxo‐dGTP by MTH1, and 3 OGG1‐mediated excision of 8‐oxo‐dG from genomic DNA." (PMID 27917618, 2017). "Seven genes out of 13 (CCNH, ERCC2, ERCC6, NEIL1, OGG1, RPA1, XPA) had a significantly different expression in tumour versus normal tissue stored in PAXgene Tissue System." (PMID 27383461, 2016). "In contrast to OGG1, XRCC1 showed significantly enhanced expression levels in the tumor samples, as well as in all clinical, histopathological data." (PMID 25268610, 2014). "The results indicate a downregulation of OGG1 and an upregulation of XRCC1 expression in tumor tissue." (PMID 25268610, 2014). "Notably, Th5487, the inhibitor of DNA binding activity of OGG1, blocks the recognition and transmission of oxidative signals, alleviates SYT7 expression and suppresses EVs release, thereby preventing tumour progression in vitro and in vivo." (PMID 39235072, 2024). "Another study found that while topical administration of OGG1 did not affect UVB-induced tumor multiplicity, it did reduce tumor size and significantly decrease tumor progression." (PMID 39063576, 2024). "We also demonstrate that OGG1 and PARG inhibitors can exacerbate the impact of high-LET protons in tumour cell killing, and therefore could represent a novel therapeutic strategy, such as in the treatment of HNSCC." (PMID 38368415, 2024).
tumor (continued). "The results show that detectable amounts chromium and chlorine in the tumor tissue, as well as the occurrence of high protein expression of OGG1/2, SOD1, Ref-1 and Trx-1 may influence the tumor growth and predict the clinical evolution of OSCC." (PMID 34785721, 2021). "It is possible that enhanced MCF-7 tumor cell killing observed with TPT and ascorbic acid observed in our previous study may, in part, have resulted from this decrease in OGG1 by TPT." (PMID 32765594, 2020). "Besides, we also observed that MSH4, NBN, NEIL2, OGG1 and XRCC2 were downregulated in both HPV-positive tumor cell lines when compared to the HPV-negative one." (PMID 30674977, 2019). "However, tumours with reduced MMR gene expression also displayed low MPG, OGG1 and PARP1 expression." (PMID 28903334, 2017). "Interestingly, taking into account the tumor stage, those patients with a more advanced grade (III and IV) showed a significant repression of APE1, OGG1 and PARP-1." (PMID 25268610, 2014). "Interestingly, when taking into account the tumor stage, patients with more advanced grades (III and IV) showed a significant repression for APE1, OGG1 and PARP-1." (PMID 25268610, 2014). "The results of this study confirmed that the expression of OGG1 protein in Ect1/E6E7 cells was significantly higher than that in SiHa cells, suggesting that OGG1 protein may also be a potential tumor suppressor protein or have tumor suppressive effect." (PMID 36726132, 2023). "As the main 8-oxoG repair enzyme, OGG1 inhibitors have also been widely studied; however, at present, treatment with OGG1 inhibitors has not produced the outstanding effects in tumor treatment seen with MTH1 inhibitors, although there were obvious effects in inhibiting inflammatory responses." (PMID 36497058, 2022). "Unlike non-malignant cells, tumor cells may better overcome the OGG1 Cys326 malfunction by upregulation of other components involved in the orchestra of antioxidative and DNA repair functions." (PMID 34199885, 2021). "Additionally, OGG1 is involved in the transcriptional regulation of nuclear factor kappa B, activation of small GTPases, and inhibition of poly (ADP-ribose) polymerase (PARP)-mediated cell death, all of which are pivotal in modulating inflammation, tumor progression, and age-related disorders." (PMID 41357210, 2025). "Although OGG1-BER protects the genome integrity by repairing the lesion or eliminating cells with malignant potential and its overexpression improves H2O2-induced cell death, in the case of TPC-1 cells, the lack of MUTYH gene expression could favor the maintenance of tumor phenotype loop." (PMID 35269445, 2022). "Since we were unable to demonstrate OGG1 target engagement in A3 cells in the derived xenograft tumor, we hypothesized that the lack of in vivo TH5487 efficacy was due to lack of OGG1 target engagement." (PMID 33211885, 2020).
adenocarcinoma (12 papers, 2006 to 2023). A common cancer characterized by the presence of malignant glandular cells. "Development of adenocarcinoma (5%) was found in one male Ogg1−/− mouse of the DMBDD group." (PMID 28820464, 2017). "Interestingly, OGG1 overexpression protects cells against Ras-induced senescence and high OGG1 expression is correlated with lower genomic instability in a panel of adenocarcinoma cell lines." (PMID 33211885, 2020). "Adenocarcinomas were found in the lungs of PB-administered Ogg1−/− males, however, were absent in the PB-treated Ogg1+/+ group." (PMID 28785378, 2017). "In addition long exposures to DSS (15 cycles) significantly increased adenocarcinoma development in the colon of Ogg1−/− in comparison to wt mice, even in the absence of carcinogen treatment." (PMID 20706593, 2010).